HES1 (hes family bHLH transcription factor 1)
Diseases named in the same sentence as HES1 in open-access papers (continued):
Sharing a sentence is not in itself a finding about the gene and the disease.
ovarian carcinoma (14 papers, 2005 to 2025). A malignant neoplasm originating from the surface ovarian epithelium. "In conclusion, Notch1-3, Jagged1 and Hes1 are more highly expressed in highly malignant ovarian cancers, and upregulation of Notch pathway component protein expression in ovarian cancer is associated with shortened overall and disease-free survival, especially in patients with advanced tumors." (PMID 40630953, 2025). "TGF-β, a crucial cytokine that induces epithelial-mesenchymal transition (EMT), can upregulate Hes1 expression in epithelial ovarian cancer." (PMID 40755759, 2025). "DAPT can downregulate the expression of Notch1 and Hes1 in a dose- and time-dependent manner, inducing growth inhibition and apoptosis in ovarian cancer A2780 cells." (PMID 40755759, 2025). "Hes1 locus is amplified in 2–25% in breast and 2–22% in ovarian cancer, followed by Hey1, Notch2 and Notch3." (PMID 31470883, 2019). "The expression of Hes1 and Hey1 also increased in galectin-3-overexpressing A2780 ovarian cancer cells." (PMID 27626163, 2016). "Future studies are needed to elucidate this MSeA-induced transcriptional regulation and to verify the role of HES1 and other Notch target genes in pre-clinical models and clinical samples of ovarian cancer." (PMID 25010594, 2014). "In summary, the Notch-signalling pathway is operative in ovarian cancer, and we propose a positive relationship between Notch pathway activation as indicated by HES1 protein expression levels and tumour growth in ovarian cancer." (PMID 16136053, 2005). "The effect of this combination on ovarian cancer stem cells was determined by the tumorsphere formation assay, while the implication of the Notch pathway was evaluated post-ectopic expression of the Hes1 gene." (PMID 31470883, 2019). "NICD interacted with HES1 or other signaling such as Ras and PI3K/Akt and played an oncogenic role in ovarian cancer." (PMID 28030808, 2017). "Intriguingly, the enforced expression of miR-199b-5p profoundly reduced HES1 luciferase reporter activity in SKOV3 cells by 35%, indicating the JAG1-Notch1 signaling cascade could be suppressed by miR-199b-5p in ovarian cancer cells." (PMID 24659709, 2014). "HES1 protein was strongly expressed in 18/19 ovarian cancers and borderline tumours but not in adenomas." (PMID 16136053, 2005). "Over-expression of NOTCH1 intracellular domain, but not HES1 or HEY1, inhibits E-cadherin expression and induces EMT in ovarian cancer cells, probably through the induction of Snail expression." (PMID 20010940, 2010). "A recent analysis of the cancer genome atlas (TCGA) ovarian cancer data, largely comprised of HGSOC samples, has shown a significant reduction in DLL1, JAG1, NOCTH4, and an increase in HES1, NOCTH1 and NOTCH3 expression in OC samples compared to normal tissues." (PMID 40002854, 2025).
adenoma (13 papers, 2005 to 2025). A neoplasm arising from the epithelium. "Among the HES family, which is associated with intestinal progenitor cells in adenoma transformation, HES1 and HES4 are a paralog pair, with other members more distantly related." (PMID 39699952, 2024). "Our data show that Hes1 is upregulated ≥2-fold in 33% of CRCs while was overexpressed in 22% in adenomas." (PMID 32211044, 2020). "Notch target genes, Hes1, Hes5, Hey1, and Hey2, were upregulated ≥2-fold in 33%, 31%, 24%, and 32% of CRCs, respectively, whereas in adenomas, they were overexpressed in 22%, 22%, 11%, and 11%, respectively." (PMID 32211044, 2020). "In concordance, decreased HES1 mRNA levels have been described both in prolactinomas and non functioning adenomas compared to normal human pituitaries." (PMID 28915655, 2017). "A study indicated that expression of Notch receptors and ligands closely follows the expression in the normal crypts, while Hes1 expression was observed uniformly in the adenomas." (PMID 28086833, 2017). "The same Notch members and Hes1, instead of Hes5, seemed upregulated in the adenomas (Notch3 only in the large intestine)." (PMID 28086833, 2017). "KrasG12D upregulates expressions of Notch2, Notch3, Notch4, Jag1 and downstream target genes Hes1, Hey1 and Hey2, and deletion of Jag1 partially suppresses KrasG12D-induced adenoma development." (PMID 29142904, 2017). "Variable mRNA expression levels of NOTCH1-4, the Notch ligand JAGGED1 and the target gene HES1 were found in non functioning adenomas, corticotropinomas and somatotropinomas independently of tumor histotype." (PMID 28915655, 2017). "A salient feature was the positive correlation found for most Notch paralogs with HES1 expression when all adenomas were considered." (PMID 28915655, 2017). "In the present study, we show that many elements of the Notch pathway are expressed in epithelial ovarian tumours with carcinomas having higher HES1 protein expression levels than adenomas indicating a stronger Notch pathway activation." (PMID 16136053, 2005). "The only existing studies in the ApcMin/+ adenomas indicated that the expression of Notch receptors and ligands was similar to that observed in the crypts, Hes1 was detected uniformly and Jagged1 was overexpressed in the tumor tissue with concomitant Notch1 and 2 activation." (PMID 28086833, 2017). "Remarkably, positive correlations between the expression of NOTCH1-2,4 and the HES1 target gene, and between NOTCH3 with the ligand JAGGED1 were found in the cohort of samples used when all adenomas were considered, independently of tumor histotype." (PMID 28915655, 2017). "Whereas Hes1 deletion in normal Lgr5+ or Bmi1+ ISCs compromised self-renewal without impacting homeostasis, deletion of Hes1 in the Lgr5+ or Dclk1+ CSCs of ApcMin/+ adenomas elicited apoptosis, alleviating tumour burden." (PMID 33673710, 2021).
melanoma (13 papers, 2011 to 2024). A malignant, usually aggressive tumor composed of atypical, neoplastic melanocytes. "Furthermore, we report for the first time that aberrant NOTCH signaling can predict clinical outcome in melanoma, with high HES1 and DLL3 levels associated with shorter post recurrence survival." (PMID 21980408, 2011). "We investigated the effect of PHB ligands on the main survival pathways in melanoma in three representative melanoma lines with different mutational status and observed that JI130 and MEL56 inhibit PHBs and the HES1 expression that express the latter." (PMID 37508519, 2023). "M1 polarized macrophages isolated from mice with melanoma tumors were seen to express increased Notch ligands, receptors and Hes1." (PMID 38269089, 2023). "Since the Notch pathway is activated in approximate 50%-60% of melanomas according to our previous study, Hes-1 stained positive in some melanoma cells can be used as internal control for MAFs which are FSP-1+." (PMID 33705467, 2021). "The strong Hes-1 expression detected in melanoma tissues (top) is from malignant melanoma cells in which the Notch pathway is activated not from MAFs, which are stained as green cells." (PMID 33705467, 2021). "Levels of Hes-1 were undetectable in 18 out of 24 melanomas and marginally measurable in only 6 melanomas (6/24, 25%)." (PMID 33705467, 2021). "In this study, we observed dysregulation of G9a in melanoma samples, repression of Notch1 and Hes1 expression via G9a inhibitor UNC0642, and inhibition of melanoma cell growth." (PMID 32015216, 2020). "Upon RO4929097 treatment, the selected melanoma cell lines showed downregulation of NOTCH downstream effector HES1, confirming the ability of the drug to affect the NOTCH signaling pathway." (PMID 21980408, 2011). "Expression of Hes-1 in fibroblasts at melanoma and normal skin tissues." (PMID 33705467, 2021). "Our data showing a downregulation of Notch signaling along the N1ICD-HES1 axis due to high NRN1 expression astonishingly suggest a tumour-suppressive role of the NRN1-Notch-Hes1 interaction in the skin and melanoma development especially." (PMID 38705997, 2024). "We next examined the impact of myeloid-specific Hes1 KO on tumor growth by subcutaneous injection of murine melanoma cells (B16F10) into WT and Hes1-cKO mice." (PMID 39702544, 2024). "In the siNRN1 knockdown, Hes1 transcription, protein levels and promoter activity were all increased, confirming the inhibitory effect of NRN1 on Notch signaling in melanoma." (PMID 38705997, 2024). "In macrophages, in vitro models of melanoma show a higher correlation of NOTCH1, NOTCH2, and Hes1 expression in M1 macrophages." (PMID 37893184, 2023). "In human primary melanoma cell lines, RO4929097 decreased the levels of NOTCH transcriptional target HES1." (PMID 21980408, 2011). "The expression of the NOTCH targets HES1 and HEY1 was reduced in RO4929097-treated tumors, together with that of putative melanoma stem cell markers." (PMID 21980408, 2011). "Western blot analyzed the expression of SOX10, Notch1, and HES1 in melanoma cell treated with or without miR-222-3p inhibitor." (PMID 35585935, 2022). "Tissue microarray slides composed of 24 cores derived from melanomas, 9 cores from adjacent and 15 cores from non-adjacent normal skin tissues, were co-stained with anti-Hes-1 and anti-FSP-1 (fibroblast specific protein-1)." (PMID 33705467, 2021). "The ratio of Hes-1: FSP-1 in melanomas, adjacent and non-adjacent skin tissues, is 0.077±0.088, 0.537±0.193 and 0.401±0.100, respectively." (PMID 33705467, 2021). "In addition, selected members of NFKB and NOTCH signaling pathways (IKBKB, NOTCH2, HES1, PRKCA) were strongly overrepresented in CD271+ melanoma-initiating cells." (PMID 31118427, 2019). "We focused our investigations on HES1 and HEY1 and not on the other existing variants, since they are the most transcribed variants in human cells and cancers and are generally the most expressed in melanoma cell lines specifically." (PMID 38705997, 2024).
melanoma (continued). "Six targets—S100A9, FLG, SAMMSON, LY6D, CACNA2D2, and HES1—were found to have variable expression in different melanoma cell lines, so they could not be validated as GLI targets in melanoma." (PMID 36139698, 2022).
neuroblastoma (12 papers, 2011 to 2025). Neuroblastoma (NB) is the most common solid, extracranial childhood tumor. "Additionally, Notch2, one of the MK receptors, was found to contribute to neuroblastoma (NB) tumorigenesis through Notch-HES1 signaling in an MK-deficient MYCN transgenic mice model for NB." (PMID 37835544, 2023). "Evidence for NOTCH1-independent HES1 expression has been demonstrated in Ewing’s sarcoma, neuroblastoma and endothelial cells through mechanisms that involve JNK signaling or HIF-1-mediated hypoxia signaling, among others." (PMID 41009728, 2025). "In neuroblastoma, the activation dynamics of the Hes1 promoter reveal CSC plasticity, stemness, and heterogeneity." (PMID 40755759, 2025). "Some experiments on neuroblastoma cancer stem cells (NBSCs) with Hes1 activated have shown, by limiting dilution, a stronger ability to form spheres compared with controls." (PMID 37686355, 2023). "The specific inhibitor of MK APT-1 significantly reduced the volume and weight of neuroblastoma and also reduced the expression of the nuclear transcription factor HES1 in the Notch2 signaling pathway." (PMID 35774607, 2022). "In neuroblastoma cells, Hes1 levels increase in a dose-dependent manner under TGF-α stimulation." (PMID 40755759, 2025). "Furthermore, transduction with HES1 of several neuroblastoma cell-lines, including IMR32 and SH-SY5Y, led to inhibition of proliferation, and growth was also inhibited by treatment with recombinant Notch ligand Jag1." (PMID 32210188, 2020). "In addition, miR-9 overexpression in a neuroblastoma cell line (N1E-115) decreased the RNA level of the murine homolog, Hes1, and conversely, inhibition of endogenous miR-9 with miR-9 LNA increased it." (PMID 21238922, 2011). "Thus, our present results suggest that a transcriptional complex of LMO3 and HEN2 may contribute to the genesis and malignant phenotype of neuroblastoma by inhibiting HES1 which suppresses the transactivation of Mash1." (PMID 21573214, 2011). "In this study, we examined whether there could exist functional relationship between LMO3/HEN2 and Mash1 in neuroblastoma, and found that LMO3/HEN2 attenuates HES1 function and enhances transactivation of Mash1, leading to aggressive phenotype of neuroblastoma." (PMID 21573214, 2011). "Notch pathway targets and effectors were highly induced in our RNA-seq of IMR32 treated with BMP4, so we first validated a panel of Notch pathway genes, including HES1, MAFB, MAML2 and NOTCH3, confirming a BMP4-Notch signaling pathway in neuroblastoma." (PMID 32210188, 2020). "In the human neuroblastoma cell line IMR32, one specific protein complex bound to the HES1 promoter −4706 to −4740 region, containing CpG sites 2–5." (PMID 25906782, 2015). "Thus, it is likely that the balance between intracellular amounts of HES1 and LMO3/HEN2 might determine expression levels of Mash1, and thereby regulating neuroblastoma cell growth." (PMID 21573214, 2011).
gastric cancer (10 papers, 2011 to 2025). A primary or metastatic malignant neoplasm involving the stomach. "Notch signaling contributes to maintaining gastric cancer stem cells, which may be associated with Hes1 expression." (PMID 28881855, 2017). "Thus, in gastric cancer, the loss of feedback regulation among Id1a, Id1b, and Hes1 may be a major cause of malignant transformation." (PMID 32974175, 2020). "Thus, the loss of feedback regulation among PTBP3, Id1, and Hes1 in gastric cancer cells may be one of the causes of inhibited differentiation and malignant proliferation of these cells." (PMID 32974175, 2020). "Conversely, Hes1 inhibition downregulates chemoresistance-associated proteins (MDR1, ABCG1/2, RAD51) in gastric cancer MKN45 spheroids." (PMID 40755759, 2025). "Hes1 emerges as a critical factor regulating gastric cancer stem cell properties, malignant behaviors, treatment resistance, and prognosis." (PMID 40755759, 2025). "Consistent results from both in vitro and in vivo experiments have demonstrated significant upregulation of Hes1 expression in gastric cancer cell lines and tissues." (PMID 40755759, 2025). "Immunohistochemistry and immunofluorescence analysis of 269 gastric cancer tissue samples revealed that 89% of them exhibited positive Hes1 expression (moderate to strong staining)." (PMID 40755759, 2025). "In conclusion, the findings of the study showed that ETSJC improved the chemosensitivity of 5-FU by blocking Notch1/Hes1 signaling pathway in gastric cancer-bearing mice." (PMID 34257696, 2021). "LY294002 in coordination with DAPT (γ-Secretase Inhibitor) inhibits Notch1, HES1, and pAkt in gastric cancer cells, thus inhibit metastasis of gastric cancer through mutual enhancement." (PMID 33958005, 2021). "MKN45 cells were induced to differentiate with NaBU and the expressions of Id1a, Id1b, PTBP3 and Hes1 (proteins closely related to the differentiation of gastric cancer cells) were detected." (PMID 32974175, 2020). "DAPT has been shown to inhibit cell proliferation, migration, and invasion of gastric cancer by inhibiting the Notch1/Hes1 pathway, and in line with the study results, decreased expression of mesenchymal markers such as vimentin and Snail in gastric cancer." (PMID 31508369, 2019). "Collectively, the Dll1-Notch1 signaling axis and the target gene Hes1 are suggested to have important roles in gastric cancer." (PMID 28881855, 2017). "In GC patients, we found a correlation between DLL1 and Hes1 expression, while DLL1 methylation and Hath1 expression were associated with the diffuse and mixed type of gastric cancer." (PMID 22249198, 2011). "Furthermore, Hes1 collaborates with the Wnt/β-catenin, Hedgehog, and mTOR pathways to promote gastric cancer progression, indicating potential for combination therapy." (PMID 40755759, 2025). "The high expression of Hes1 protein promotes the proliferation of gastric cancer cell lines." (PMID 38544826, 2024). "This phenomenon may be related to the inhibition of Notch1/Hes1 signaling pathway; it provides a potential therapeutic method to improve the chemosensitivity of 5-FU in gastric cancer." (PMID 34257696, 2021). "Hes1 expression has been found in several gastric cancer cell lines." (PMID 32974175, 2020). "HEYL could also form heterodimeric complexes with HES1, an oncogene in many cancer types including gastric cancer, to regulate gene expression under transcription level." (PMID 32463580, 2020). "Similarly, using another gastric cancer stem cell marker, CD44, Notch1 and Hes1 were found to be highly expressed in gastric cancer stem-like cells (GCSCs)of MKN45 cells." (PMID 28881855, 2017). "Based on these studies, inhibition of Hes1 may be a promising way to attenuate stemness of gastric cancer cells." (PMID 28881855, 2017).
gastric cancer (continued). "Additionally, Notch1, Notch3, Jagged1, Jagged2 and Hes1 are expressed primarily at the isthmus of gastric mucosa, based on immunohistochemical analysis, and are expressed significantly less in normal gastric tissue compared to gastric cancer tissues." (PMID 28881855, 2017). "High Hes1 expression also confers resistance to EGFR-TKIs (trametinib, lapatinib) in low-grade serous ovarian cancer, gastric cancer, and lung adenocarcinoma." (PMID 40755759, 2025). "For instance, γ-secretase inhibitors (GSIs) can simultaneously suppress Notch/Hes1 and Wnt/β-catenin signaling, effectively inhibiting the proliferation, migration, and invasion of CD44(+) gastric cancer stem cells (GCSCs) and inducing apoptosis." (PMID 40755759, 2025). "In gastric cancer, simultaneous blockade of Notch (using DAPT) and PI3K/Akt signaling (using LY294002) can synergistically inhibit the expression of Notch1, Hes1, and p-Akt, significantly suppressing tumor metastasis." (PMID 40755759, 2025). "Downregulation of Hes1 through DAPT or siRNA can inhibit Snail expression, impair EMT, and attenuate the proliferation, migration, invasion, and chemoresistance of gastric cancer cells." (PMID 40755759, 2025). "Although Hes1 inhibited the activity of the PTBP3 promoter, it failed to impact the protein expression of PTBP3, showing the complexity of gene expression regulation in gastric cancer cells." (PMID 32974175, 2020).
liver cancer (10 papers, 2016 to 2024). An epithelial or non-epithelial malignant neoplasm that arises from the liver. "XH regulated the MCP-1 protein and reduced the expression of Notch1 and HES-1 protein in liver cancer." (PMID 33923053, 2021). "The data clearly demonstrated that serotonin treatment increased the expression of Notch target Hes1 in both cell lines by 3 to 4 fold compared with control cells suggesting that serotonin activates the Notch signaling pathway in liver cancer cells." (PMID 30409162, 2018).